NCOA5 (nuclear receptor coactivator 5)
Description:
Nuclear receptor coregulator that can have both coactivator and corepressor functions. Interacts with nuclear receptors for steroids (ESR1 and ESR2) independently of the steroid binding domain (AF-2) of the ESR receptors, and with the orphan nuclear receptor NR1D2. Involved in the coactivation of nuclear steroid receptors (ER) as well as the corepression of MYC in response to 17-beta-estradiol (E2).
Synonyms: CIA; bA465L10.6
Tractability: Small molecule: a structure with a bound ligand is known. PROTAC: ubiquitination databases record sites on it; its protein half-life has been measured.
Gene: Protein-coding gene on chromosome 20 (46,060,985 to 46,089,962, reverse strand). Ensembl gene ENSG00000124160.
Subcellular location: Nucleus
Subcellular location (Human Protein Atlas): Actin filaments; Nucleoplasm
Gene Ontology:
Molecular function: protein binding; RNA binding; transcription corepressor activity; chromatin binding
Biological process: negative regulation of transcription by RNA polymerase II; regulation of signal transduction
Cellular component: actin cytoskeleton; extracellular region; nucleoplasm; nucleus
Genetic constraint (gnomAD): Loss-of-function variants: 12 observed, 60.52 expected, observed/expected ratio (o/e) 0.2, 90% interval 0.13 to 0.32. The upper end of that interval is the gene's LOEUF score, 0.32, which puts it in group 1 of 6, group 1 being the genes least tolerant of losing a copy. Missense variants: 655 observed, 799.77 expected, observed/expected ratio (o/e) 0.82, 90% interval 0.77 to 0.87. Synonymous variants: 270 observed, 288.38 expected, observed/expected ratio (o/e) 0.94, 90% interval 0.85 to 1.04.
Homologues: Orthologues: chimpanzee NCOA5 (99% identical), macaque NCOA5 (98% identical), pig NCOA5 (96% identical), dog NCOA5 (95% identical), guinea pig NCOA5 (94% identical), rabbit NCOA5 (94% identical), mouse Ncoa5 (93% identical), rat Ncoa5 (91% identical), tropical clawed frog ncoa5 (64% identical), zebrafish ncoa5 (41% identical), Drosophila melanogaster Neos (16% identical).
Diseases named in the same sentence as NCOA5 in open-access papers:
NCOA5 is named in the same sentence as 29 diseases in open-access papers, as found by Europe PMC text mining. Sharing a sentence is not in itself a finding about the gene and the disease. The quoted sentences say what the papers report.
breast carcinoma (6 papers, 2017 to 2024). "Overexpression of NCOA5 is significantly associated with progression and worse prognosis in human breast cancer, and patients with low NCOA5 expression level have significantly higher overall survival." (PMID 35984577, 2022). "Conversely, NCOA5 has been found to be upregulated in luminal breast cancer and associated with lower overall survival." (PMID 29296214, 2017). "NCOA5 expression is downregulated in breast cancer cells, which promotes the proliferation and survival of cancer cells." (PMID 37197435, 2023). "Identical, NCOA5 low expression is associated with esophageal squamous cell carcinoma.However, previous studies have already demonstrated that NCOA5 was involved in tumorigenesis in several types of cancer including breast cancer and colorectal cancer." (PMID 37197435, 2023). "Previous researches revealed that NCOA5 expression were related to breast cancer and colorectal cancer." (PMID 37197435, 2023). "More recently, NCOA5 has been found to be upregulated in luminal breast cancer, which is consistent with our report." (PMID 29296214, 2017). "In addition, we found that the expression of both WDR26 and NCOA5 increased over the progression of breast cancer and were enriched in highly aggressive and poorly differentiated grade three tumours compared with grade 1 and 2 cases." (PMID 33056990, 2020). "For instance, CARM1 is found to be overexpressed in breast cancer and prostate carcinoma, mediator complex subunit 19 (MED19) is upregulated in bladder cancer, and nuclear receptor co-activator 5 (NCOA5) expression is elevated in colorectal cancer." (PMID 39343952, 2024).
colorectal cancer (6 papers, 2017 to 2024). A primary or metastatic malignant neoplasm that affects the colon or rectum. "NCOA5 also enhances the sensitivity of colorectal cancer cells to chemotherapy drugs, thereby improving the therapeutic efficacy." (PMID 37197435, 2023). "Moreover, NCOA5 has been shown to suppress the growth and metastasis of colorectal cancer cells by inhibiting the activation of the PI3K/Akt signaling pathway." (PMID 37197435, 2023). "Moreover, NPM1 contributed to cell proliferation through phosphatase and tensin homologue deleted on chromosome ten (PTEN) inactivation, while NCOA5 promoted proliferation, migration and invasion of colorectal cancer cells via activation of PI3K/Akt pathway." (PMID 34922560, 2021). "Expression level of NCOA5 in colorectal carcinoma (CRC) tissues is much higher than that in adjacent tissues." (PMID 35984577, 2022).
hepatocellular carcinoma (6 papers, 2017 to 2025). A malignant tumor that arises from hepatocytes. "Interestingly, a previous study revealed that NCOA5 insufficiency increases the risk of both glucose intolerance and inflammatory phenotype, resulting in the development of hepatocellular carcinoma (HCC)." (PMID 29296214, 2017). "Previous studies revealed that NCOA5 insufficiency increases the risk of both glucose intolerance and inflammatory phenotype, resulting in the development of hepatocellular carcinoma (HCC)." (PMID 37197435, 2023). "Conversely, It has also been reported that NCOA5 expression is downregulated in hepatocellular carcinoma, esophageal squamous cell carcinoma, papillary thyroid carcinoma, and cervical cancer." (PMID 37197435, 2023). "Besides, NCOA5 expression is significantly decreased in hepatocellular carcinoma cells compared to normal tissues." (PMID 37197435, 2023). "Ncoa5+/− male mice developed glucose intolerance, hepatic steatosis and hepatocellular carcinoma (HCC), which can be partially reversed by heterozygous deletion of Il-6 gene." (PMID 31664153, 2019). "NCOA5 has been identified as a crucial factor in the progression of hepatocellular carcinoma (HCC)." (PMID 40316542, 2025).
Glucose intolerance (4 papers, 2017 to 2023). Glucose intolerance (GI) can be defined as dysglycemia that comprises both prediabetes and diabetes. "Reduced expression of NCOA5 has been associated with carcinogenesis, glucose intolerance (T2D), stem cell function as well as proinflammatory and profibrotic alterations of the micromilieu." (PMID 37624790, 2023). "We previously reported that the mRNA and protein levels of IL-6 were elevated in the liver of Ncoa5+/− male mice and that heterozygous deletion of Il-6 gene rescued glucose intolerance and hindered HCC development in Ncoa5+/− male mice." (PMID 31664153, 2019).
esophageal squamous cell carcinoma (2 papers, 2017 to 2023). Esophageal squamous cell carcinoma (ESCC) is a type of esophageal carcinoma (EC) that can affect any part of the esophagus, but is usually located in the upper or middle third. "Other research also found that NCOA5 is decreased in esophageal squamous cell carcinoma (ESCC), which is associated with its progression and a potential biomarker in predicting poor prognosis." (PMID 29296214, 2017).
laryngeal carcinoma (2 papers, 2024 to 2025). Carcinoma that arises from the laryngeal epithelium. "Next, the effects of NCOA5 expression on proliferation, migration and invasion of laryngeal cancer cells were verified." (PMID 39741976, 2024). "The expression of PRMT1 and NCOA5 was inhibited by siRNA mediated gene knockdown in laryngeal cancer cells." (PMID 39741976, 2024). "The present study aimed to investigate how PRMT1-mediated H4R3me2a methylation affects the proliferation, migration and invasion of laryngeal cancer cells and to verify the role of NCOA5 in this process." (PMID 39741976, 2024). "The results showed that after knocking down NCOA5, the level of H4R3me2a significantly decreased, and the proliferative and migratory abilities of laryngeal carcinoma cells were weakened." (PMID 39741976, 2024). "All these results indicated that NCOA5 overexpression promoted the proliferation, migration and invasion of laryngeal cancer cells." (PMID 39741976, 2024). "All these results indicated that NCOA5 knockdown inhibited the proliferation, migration and invasion of laryngeal cancer cells." (PMID 39741976, 2024). "PRMT1, as a protein arginine methyltransferase, may directly affect the stability or function of NCOA5 through methylation modification, thus influencing the proliferation, migration, and invasive abilities of laryngeal carcinoma cells." (PMID 39741976, 2024). "Additionally, transcriptome sequencing of laryngeal carcinoma cells with PRMT1 knockdown revealed a significant decrease in NCOA5 expression." (PMID 39741976, 2024). "PRMT1 and NCOA5 play important roles in the development of laryngeal carcinoma and provide new insights for developing therapeutic strategies targeting PRMT1 and NCOA5." (PMID 39741976, 2024). "Similarly, in laryngeal cancer, PRMT1 modulates nuclear receptor coactivator 5 (NCOA5) expression via H4R3me2a, facilitating tumor cell proliferation, migration, and invasion." (PMID 41256732, 2025). "NCOA5 may maintain normal levels of H4R3me2a by promoting the recruitment of PRMT1 to specific gene loci or enhancing its activity, thereby regulating the proliferation and migration of laryngeal carcinoma cells." (PMID 39741976, 2024).
autoimmunity diseases (1 paper, 2017). "We conclude that the NCOA5 gene may be a good candidate for future studies investigating genetic tendencies for chronic inflammatory and autoimmunity diseases that share similar pathogenic pathways." (PMID 28694762, 2017).
gastric cancer (1 paper, 2023). A primary or metastatic malignant neoplasm involving the stomach. "It has been demonstrated that NCOA5 inhibits the proliferation, migration, and invasion of gastric cancer cells by suppressing the expression of matrix metalloproteinases (MMPs)." (PMID 37197435, 2023).
genital ulceration (1 paper, 2017). "Namely, we found that TT genotype and the T allele of the NCOA5 rs2903908 polymorphism were related to an increased (approximately one and half-fold) susceptibility to BD and it has a protective role for genital ulceration and uveitis in this study." (PMID 28694762, 2017). "The CT genotype of the NCOA5 rs2903908 polymorphism was significantly higher in BD patients with genital ulceration (p=0.002, OR=3.03, 95 % CI=1.51-6.08), and the TT genotype was higher in BD patients without genital ulceration (p=0.014, OR=0.46, 95 % CI=0.25-0.84)." (PMID 28694762, 2017).
Infertility (1 paper, 2019). "Given the role of NCOA5 in ERα-mediated transcription, NCOA5 deficiency might possibly influence expression of other genes regulated by ERα, contributing to the development of infertility." (PMID 31664153, 2019). "Taken together, these results suggest that Ncoa5+/− male mice are infertile, at least in part, due to a decrease in the number of motile sperm." (PMID 31664153, 2019). "Here we report that heterozygous deletion of the nuclear receptor coactivator-5 (Ncoa5) gene resulted in decreased motility and progression of spermatozoa in the cauda epididymis, leading to infertility in male mice." (PMID 31664153, 2019). "Furthermore, heterozygous deletion of Il-6 gene in Ncoa5+/− male mice partially improved spermatozoa motility and moderately rescued infertility phenotype." (PMID 31664153, 2019).
male infertility (1 paper, 2019). The inability of the male to effect fertilization of an ovum after a specified period of unprotected intercourse. "Our results suggest a critical role of NCOA5 in epididymal sperm maturation and further implicate NCOA5 deficiency as a possible etiological risk in human male infertility." (PMID 31664153, 2019). "Our results uncover a previously unknown physiological role of NCOA5 in the regulation of epididymal sperm maturation and suggest that NCOA5 deficiency could cause male infertility through increased IL-6 expression in epididymis." (PMID 31664153, 2019).
ovarian carcinoma (1 paper, 2023). A malignant neoplasm originating from the surface ovarian epithelium. "We suggest that NCOA5 gene may have potential value as a pathological diagnostic marker of ovarian cancer." (PMID 37197435, 2023). "Our study reveals that NCOA5 has great potential as a novel prognostic marker in ovarian cancer." (PMID 37197435, 2023). "However, the association between NCOA5 and ovarian cancer and its underlying mechanisms has not been reported yet." (PMID 37197435, 2023). "The expression of NCOA5 in ovarian cancer and its role in tumor development remain unclear." (PMID 37197435, 2023). "Due to heterogeneity between different databases, differences between study populations NCOA5 is not listed as a prognostic marker in ovarian cancer at present in protein atlas database." (PMID 37197435, 2023). "The expression level of NCOA5 in FIGO stage III/IV was significantly higher than that in FIGO stage I/II patients, indicating that NOCA5 may play a role in the distant metastasis of ovarian cancer, however, it needs to be verified by cell experiments." (PMID 37197435, 2023).
serous ovarian cancer (1 paper, 2023). "What calls for special attention is that the expression level of NCOA5 was significantly higher in serous ovarian cancer than in other EOC (P<0.001)." (PMID 37197435, 2023). "NCOA5 may be a promising supplementary marker in serous ovarian cancer and help determine its management in the future." (PMID 37197435, 2023). "NCOA5 was highly expressed in serous ovarian cancer and closely related to CA125 and HE4." (PMID 37197435, 2023).
uveitis (1 paper, 2017). An inflammatory process affecting a part of or the entire uvea. "Finally, we found that the BD patients who are carrying the C allele at the NCOA5 rs2903908 locus may be more prone to developing uveitis." (PMID 28694762, 2017).
tumor (8 papers, 2017 to 2025). "High expression of NCOA5 was notably associated with the length of tumor (P<0.001), regional lymph node staging (P=0.005) and cancer staging (P=0.018), suggesting that NCOA5 positively modulates malignant progression of CRC." (PMID 29296214, 2017). "Among these CRC tumor tissue samples, fifty-five cases (78.6%) showed high expression of NCOA5 (32 samples scored “+++”, and 23 samples scored “++”) and fifteen cases showed low expression of NCOA5 (13 samples scored “+”, and 2 samples scored “-”)." (PMID 29296214, 2017). "Moreover, NCOA5 has been found to suppress the expression of cancer stem cell markers, thereby inhibiting tumor growth and metastasis." (PMID 37197435, 2023). "Correlation analysis between NCOA5 expression and other tumor markers." (PMID 37197435, 2023). "In addition, NCOA5 as a corepressor can cooperate with TIP30 tumor suppressor and subsequently inhibit ERα-induced c-myc transcription." (PMID 29296214, 2017). "Moreover, LY294002 and knockdown of Cyclin D1 or MMP9 remarkably blocked the tumor-promoting activity of NCOA5." (PMID 29296214, 2017). "This study investigates the expression of NCOA5 in HCC, revealing its significant overexpression in tumor tissues compared to healthy liver tissues, as evidenced by analysis of the TCGA dataset and RT-qPCR in patient samples." (PMID 40316542, 2025). "The top 5 proteins exclusively detected in tumor in ≥ 90% of the cases included CD68 (a macrophage marker), Optineurin (OPTN), Nuclear receptor coactivator 5 (NCOA5), RAP1GDS1 (Rap1 GTPase-GDP dissociation stimulator 1) and Stromal cell derived factor 2 like 1 (SDF2L1)." (PMID 36508875, 2023). "Herein, we demonstrated that expression of NCOA5 in human CRC tissues was notably higher than that in adjacent tissues, which significantly correlated with clinicopathological features such as length of tumor, regional lymph node staging and cancer staging." (PMID 29296214, 2017). "Furthermore, we investigated the effects of NCOA5 on CRC cell proliferation, migration and invasion in vitro and CRC subcutaneously (s.c.)xenografted tumor growth in vivo by lentivirus-mediated NCOA5 knockdown and overexpression, and also elucidated the potential molecular mechanisms." (PMID 29296214, 2017). "To further assess whether the effect of NCOA5 on in vitro growth of CRC cells could be reproduced in vivo, we monitored and compared human CRC s.c. xenografted tumor growth of SW620-shNCOA5 3# vs SW620-shNTC, and SW480-LV-NCOA5 vs SW480-LV in athymic BALB/c nude mice." (PMID 29296214, 2017).
cancer (7 papers, 2015 to 2025). A tumor composed of atypical neoplastic, often pleomorphic cells that invade other tissues. "NCOA5 plays a critical role in the occurrence and development of several cancers by regulating various cellular processes such as cell proliferation, differentiation, and apoptosis." (PMID 37197435, 2023). "LH + DDP further reduced the expression level of NCOA5 in cancer cells, which is consistent with the enhancement of anticancer efficacy in LH + DDP group." (PMID 35984577, 2022). "Accumulating evidence has shown that NCOA5 is downregulated in certain types of human cancers such as HCC and ESCC." (PMID 29296214, 2017). "We selected those genes with functions known to be associated with cancer of which there were 12—SNVs: NOTCH2, PIK3CG, IL2RB, BAI3, FREM2 and RERE; indels: UTRN, CDHR3, NCOA5, CABYR, HOTAIR and FOLH1." (PMID 26017033, 2015). "Nuclear receptor coactivator 5 (NCOA5) plays a significant role in the progression of human cancer." (PMID 37197435, 2023). "Therefore, NCOA5 may serve as a potential therapeutic target for the treatment of cancers." (PMID 37197435, 2023). "However, the roles of NCOA5 in human cancers are largely unknown." (PMID 29296214, 2017). "NCOA5 and ANP32B were reported previously in various cancer types." (PMID 30779739, 2019).
NCOA5 also shares sentences with these, for which no sentence is quoted: diabetes (3 papers); diabetes mellitus type 2 (2); atrial fibrillation (1); Behçet's disease (1); bladder cancer (1); cervical cancer (1); invasive breast carcinoma (1); lymph node metastasis (1); Obesity (1); papillary thyroid carcinoma (1); prostate carcinoma (1); psoriasis (1); urological diseases (1).